INS (insulin)
Diseases named in the same sentence as INS in open-access papers (continued):
Sharing a sentence is not in itself a finding about the gene and the disease.
Obesity (continued). "In the CALERIE-2 trial, both groups showed improvement in fasting insulin levels and the related HOMA-IR but neither group showed a change in cognitive performance, suggesting that obesity and its metabolic effects at baseline may be necessary for an effect on cognitive function to occur." (PMID 40805992, 2025). "These previous experiments were conducted in vitro, and whether differences in systemic FA availability among adults with obesity may contribute to modifications in CD36 recruitment of Fyn to IRβ and modify IRβ phosphorylation and downstream insulin action in human skeletal muscle is not known." (PMID 39487600, 2025). "As an EDC, bisphenol A can disrupt the endocrine regulation of the body, especially affecting insulin sensitivity, EDC has a negative impact on endogenous hormones, and subsequently affects the release of cytokines and growth factors, thereby influencing the occurrence and progression of obesity." (PMID 41226680, 2025). "Additionally, a study simulating hyperinsulinemia and hyperlipidemia in non-obese women showed that elevated insulin and lipid levels can acutely suppress LH and FSH, providing a possible mechanism for the relatively hypogonadotropic hypogonadism observed in obesity." (PMID 39696159, 2024). "In the present study, resveratrol improved insulin-mediated signal transduction [insulin-stimulated phosphorylation of IRS1 (Tyr632), Akt (Ser473), and TBC1D4 (Thr642)] in the myotubes from lean individuals, but not in the myotubes from individuals with severe obesity." (PMID 38324260, 2024). "This suggests that the improved insulin sensitivity observed in Gpr75–/– mice under prolonged HFD feeding was a secondary effect of the reduced adiposity and that the resistance of Gpr75–/– mice to HFD-induced obesity was not due to enhanced insulin sensitivity but rather decreased food intake." (PMID 39137039, 2024). "However, in the current study of adults without obesity, the lack of positive correlations suggests that postprandial increases in plasma LEAP2 are not driven by postprandial increases in plasma glucose, serum insulin, or triglycerides." (PMID 37287649, 2023). "It has been previously reported that obesity is accompanied by increased linear growth, which might be due to the effect of insulin on IGF-1 receptor, and that children with obesity are taller for their age, although they do not usually tend to attain taller height as adults." (PMID 37862340, 2023). "Diet-induced obese mice showed greater anxiety, more inflammation, and less insulin signaling in the nucleus accumbens than the controls; yet anti-inflammatory treatment diminished this anxiety and inflammation and improved insulin signaling but did not reverse HFD-induced obesity." (PMID 37443828, 2023). "Some studies were also conducted in patients with obesity or metabolic syndrome, showing that acute administration of β-glucan enriched foods dose-dependently increases PYY, increases CCK without affecting ghrelin, or decreases GIP without affecting insulin, GLP-1, or ghrelin." (PMID 36832775, 2023). "However, not every child with obesity exhibits observed hyperinsulinemia and might not enhance the effect of an LGI diet in terms of reducing fasting plasma insulin." (PMID 37761441, 2023). "Although in our study we could not correlate insulin with other variables, there is a general agreement that serum insulin together with NEFA concentrations, might be good parameters for following up animals prone to obesity and insulin dysfunction." (PMID 36290249, 2022). "In contrast, women with obesity do not increase their RMR in the luteal phase, which could lead to increased body weight and metabolic deterioration due to a higher glycemic load in a phase where a lower sensitivity to insulin has also been reported." (PMID 35631136, 2022).
Obesity (continued). "Nonetheless, the assessment of insulin action may be clinically relevant in GDM and even in pregnant women with overweight, obesity or with signs of dysglycemia (though in the absence of overt GDM), since the degree of insulin resistance can drive specific therapeutic intervention and care." (PMID 36258194, 2022). "Moreover, increased glycemic variability may also be related to lower levels of fasting C-peptide, longer diabetic duration in T2D using insulin, older age, obesity, higher TG, lower LDLC and the use of sulfonylurea in T2D without insulin treatment." (PMID 34556157, 2021). "At the same time, levels of plasma insulin and HOMA-IR in the patients with T2DM+obesity did not significantly differ from that of the patients with T2DM+obesity+CP, suggesting important contribution of obesity to IR progression in T2DM in this cohort of patients." (PMID 35221617, 2021). "Given the role of obesity and WAT inflammation in impaired glucose metabolism, we next evaluated the effect of omega-3 PUFAs on glucose homeostasis; it was improved specifically in krill oil-supplemented mice (i.e., ω3PL and ω3PL-R), as evidenced by lower FBG and non-fasting plasma insulin." (PMID 33572810, 2021). "Our study demonstrated that the tautomerase activity-lacking of MIF significantly alleviated HFD-induced obesity in mice, in which the alleviation may be related to the inhibition of the HFD-induced inflammation and insulin resistance in adipose tissues by the lack of MIF tautomerase activity." (PMID 32265835, 2020). "In this study db/db mice had pronounced hyperglycaemia and obesity; under our setup, treatment with metformin did not affect blood glucose and insulin levels, indicating that metformin-induced changes in TMAO levels are at least partially independent of glucose and insulin plasma concentrations." (PMID 32884086, 2020). "After nine weeks of HFD and with obesity established in C57BL/6 mice, we observed that a daily treatment with alliin for 3.5 weeks (15 mg/kg) did not affect body weight, but significantly improved insulin sensitivity and glucose tolerance, both evaluated through a blood glucose monitoring system." (PMID 32120804, 2020). "Thus, the interaction between insulin and resistin we observed in the rats fed the HFD occurs within the brain even in the absence of overt obesity, suggesting that high fat diets can influence the pathways mediating the changes in RSNA even in the absence of overt obesity." (PMID 30804811, 2019). "To clarify whether metabolic programming effects are due to mild maternal hyperglycemia without confounding obesity, we investigated wild-type offspring of INSC93S transgenic pigs, which are a novel genetically modified large-animal model expressing mutant insulin (INS) C93S in pancreatic β-cells." (PMID 31308048, 2019). "A mouse metabolic study comparing the effects of inflammation from HFD with diet-induced obesity and from DSS exposure showed DSS exposure increased cytokines IL-1β and IL-12p40 in the liver, mesenteric fat, and subcutaneous fat, without effects on glucose or insulin." (PMID 31179345, 2019). "Circulating levels of adiponectin were notably reduced (hypoadiponectinemia) under conditions of obesity, IR, and T2DM, whereas overexpression or administration of adiponectin improved overall insulin action and reversed hyperglycemia in obese mice, independent of plasma insulin levels." (PMID 28659972, 2017). "Importantly, the fold changes in insulin and leptin levels in our mouse model are in the same range as those in DIO mouse models of EI of metabolic phenotypes, showing the validity of our approach to alter those hormone levels in the absence of obesity." (PMID 26662513, 2016).
Obesity (continued). "We have further shown, in this model, that plasma testosterone and insulin are positively correlated with fasting and non-fasting plasma TG and apoB48, consistent with the role of these lipogenic mediators in the development of dyslipidemia in PCOS, insulin resistance, and obesity." (PMID 27777929, 2016). "In obese ob/ob mice, in which a defect in the leptin gene results in hyperphagia and subsequent obesity, genetic ablation of GIPR improved not only obesity by increasing energy expenditure, but also insulin insensitivity and glucose tolerance without seriously affecting insulin secretion." (PMID 26075286, 2015). "There were significant differences in the metabolic variables between comparison groups, with higher levels of glucose, insulin, and triglycerides, higher values of HOMA-IR, and lower HDL levels and Matsuda Index values in subjects with obesity in comparison with subjects without obesity." (PMID 24383894, 2014). "Supporting these results, glucose and insulin tolerance tests (GTT and ITT respectively) did not reveal any major differences between the genotypes, thus indicating that the depletion of mTORC2 function alone does not deeply affect insulin sensitivity in the context of leanness and obesity in vivo." (PMID 24740015, 2014). "However, when fed high fat diet (HFD), MCT1+/− mice displayed resistance to development of diet-induced obesity (24.8% lower body weight after 16 weeks of HFD), as well as less insulin resistance and no hepatic steatosis as compared to littermate MCT1+/+ mice used as controls." (PMID 24367518, 2013). "3-month old SERT−/− mice did not display obesity and hepatic steatosis (data not shown), but their IRS1 and AKT responses to insulin stimulation were reduced, further indicating that SERT−/− mice develop insulin resistance prior to a significant increase in the adiposity." (PMID 22412882, 2012). "Additionally, IPA lowers circulating glucose and insulin levels in a IPA-rich regular chow diet, and long-term HFD feeding reduces tryptamine levels in the liver, cecum, and serum of mice; however, none of these have successfully demonstrated anti-obesity effects." (PMID 39941095, 2025). "However, obesity may promote the development of MDD following the activation of pathophysiological mechanisms (inflammation, insulin/leptin resistance, and hypertension) with a negative impact on the neuroimmune status and the neural circuits controlling mood/emotional states." (PMID 40407628, 2025). "In vivo study revealed that they improved the plasma lipid profile, insulin sensitivity, and glucose metabolism without altering food intake, suggesting that B. bifidum DS0908 and B. longum DS0950 and their culture supernatants might mitigate the clinical onset of obesity." (PMID 36457182, 2023). "Although fetal glucose and insulin levels were not evaluated on PD 19, fetal hyperinsulinemia has been reported in the offspring of STZ-treated dams in late pregnancy and might contribute to the programming of macrosomia and obesity vulnerability later in life." (PMID 37396180, 2023). "Additionally, another study also reported that impaired insulin sensitivity was not present among youth in the prediabetic range, hence signifying that IFG among children with obesity may be a less important driver of morbidity and mortality than that in adults." (PMID 35370951, 2022). "The relation between overweight/obesity and cancer is still not fully clarified; the tumor environment could be metabolically stimulated by the excess of adipose tissue, with elevated levels of free fatty acids (FFA) and triglycerides, increased blood glucose, and insulin resistance." (PMID 35276833, 2022). "However, the mechanisms by which insulin regulates oocyte development have not been well established in vivo, despite evidence that insulin is involved in androgen production, gonadotropin signaling, PCOS (Polycystic Ovary Syndrome), and obesity-induced infertility." (PMID 31009498, 2019).
Obesity (continued). "The detrimental effects of the HCHF diet on glucose-insulin axis function could no longer be visualized in the young adult sheep (only females were studied at this age) after they had been fed a moderate (and for HCHF sheep: obesity correcting) diet for 1.5-years." (PMID 23755234, 2013).
Hyperglycemia (11,557 papers, 2000 to 2026). An increased concentration of glucose in the blood. "Severe chronic hyperglycaemia ( > 15 mM) causes impaired glycolytic and mitochondrial metabolism in pancreatic β-cells, leading to dramatically reduced insulin secretion and content." (PMID 42062260, 2026). "He subsequently developed marked hyperglycemia associated with impaired endogenous insulin secretion, necessitating temporary regular insulin administration and sitagliptin combination therapy." (PMID 41654851, 2026). "Glucose metabolism impairment initially manifests as postprandial hyperglycemia due to the loss of the first phase of insulin secretion." (PMID 41545622, 2026). "CC supplementation was associated with attenuation of hyperglycemia and oxidative stress, together with modulation of insulin- and hormone-related transcriptional markers." (PMID 42040401, 2026). "Autoantibodies bind to postprandial insulin, initially sequestering it and causing transient hyperglycemia." (PMID 41589093, 2026). "At the same time, blood glucose management should be strengthened simultaneously, and the insulin regimen should be actively adjusted to reduce further damage to BSCB caused by hyperglycemia." (PMID 41496012, 2026). "Hypokalemia has been linked to reduced insulin secretion, impairing pancreatic β-cell function and worsening hyperglycemia in obese individuals." (PMID 40136609, 2025). "Hyperglycemia is caused by the malfunctioning or destruction of the pancreas and insulin-producing β-cells, leading to inadequate insulin secretion." (PMID 40766758, 2025). "GH is a rare but important condition caused by excessive hepatic glycogen accumulation due to hyperglycaemia and insulin administration." (PMID 40949171, 2025). "Some studies suggest a potential association between the use of DTG‐based regimens and an elevated risk of hyperglycaemia, possibly influenced by their effects on insulin sensitivity and glucose metabolism." (PMID 40289329, 2025). "Further research has demonstrated Rg5’s capacity to improve insulin sensitivity and attenuate hyperglycemia-associated damage in diabetic settings." (PMID 40709093, 2025). "Clinical evidence indicates that males exhibit heightened susceptibility to fasting hyperglycemia, exaggerated postprandial glucose excursions, earlier onset of IR, and 30% lower insulin sensitivity than age-matched premenopausal females." (PMID 40429918, 2025). "CIII knockout defects were the most diabetogenic; they caused early hyperglycemia, glucose intolerance, and loss of glucose-stimulated insulin secretion in vivo”." (PMID 40243540, 2025). "The subsequent loss of insulin production results in hyperglycemia, muscle wasting, and vascular dysfunction." (PMID 40429969, 2025). "Type 1 diabetes (T1D) is an autoimmune disorder that causes selected destruction of insulin-secreting pancreatic beta cells leading to insulin deficiency, hyperglycemia, and long-term complications." (PMID 41328309, 2025). "Our group recently showed that glycaemic variability is increased in diabetic cats with insulin-induced post-hypoglycaemic hyperglycaemia, which is associated with higher insulin dose, higher fructosamine concentrations and a lower remission rate." (PMID 41204810, 2025). "We found that altered DNA methylation that affects insulin secretion underlies the transgenerational inheritance of hyperglycemia." (PMID 39934105, 2025). "DM in WS1 is considered similar to T1DM, as both are insulin-deficient and require insulin treatment to control hyperglycemia." (PMID 40988749, 2025). "DM comprises a group of complex metabolic disorders characterized by chronic hyperglycemia resulting from either deficient insulin secretion, impaired insulin action, or both pathological mechanisms." (PMID 41181144, 2025). "T1DM arises from a malfunction of the body’s immune system, destroying insulin-producing pancreatic β-cells, resulting in a deficiency of insulin and hyperglycemia." (PMID 39996906, 2025).
Hyperglycemia (continued). "Insufficient insulin secretion resulting from either loss of β cell mass in type 1 diabetes or β cell dysfunction in type 2 diabetes (T2D) manifests as hyperglycemia and contributes to increased morbidity and mortality." (PMID 40526441, 2025). "Newer CGMS devices, such as the Freestyle Libre (Abbott), enable rapid adjustments to insulin therapy, reducing the risk of both hypoglycaemia and hyperglycaemia." (PMID 41204810, 2025). "In patients with GDM, factors or conditions that lead to maternal pancreatic β-cell dysfunction or delayed β-cell response result in reduced insulin secretion, ultimately causing maternal hyperglycemia." (PMID 40951428, 2025). "It is a metabolic disorder characterised by high blood glucose levels (hyperglycaemia) caused by inadequate insulin action in the blood—insulin resistance." (PMID 41614781, 2025). "Chronic intermittent hypoxia is known to interfere with lipid biosynthesis, hinder insulin sensitivity, and disrupt the normal diurnal rhythm, leading to hyperglycemia and increasing the susceptibility of pancreatic β cells to damage induced by hypoxia." (PMID 40283443, 2025). "AP is frequently associated with IR and hyperglycemia, particularly in severe cases, where pancreatic function is compromised, leading to reduced insulin secretion capacity." (PMID 40937420, 2025). "It leads to insulin deficiency and hyperglycemia, requiring lifelong insulin therapy to maintain glucose homeostasis." (PMID 41156550, 2025). "PCCs can also cause mild hyperglycemia by increasing glucagon release and raising insulin resistance." (PMID 40584808, 2025). "On the other hand, studies demonstrate that increasing dietary fat causes early postprandial glucose reduction but late hyperglycemia, requiring additional insulin dosing of 6–21% depending on fat content." (PMID 41228423, 2025). "T1DM is characterized by elevated blood glucose levels (hyperglycemia) caused by deficient insulin production due to the destruction of the β-cells of the pancreatic islets of Langerhans, predominantly because of autoimmune inflammation." (PMID 40430501, 2025). "When β-cell compensatory mechanisms fail to meet the increased insulin demand, hyperglycemia develops, characterizing the hallmark metabolic disruption of GDM." (PMID 40076938, 2025). "UPFs are also rich in refined carbohydrates, leading to postprandial hyperglycemia, closely associated with disturbances in glucose, insulin, and lipid metabolism, crucial factors in liver fat increase." (PMID 40151346, 2025). "For instance, mutations in the insulin gene (INS) can result in neonatal diabetes mellitus, which is characterized by the presence of hyperglycemia within the initial six months of life." (PMID 40862129, 2025). "Control of hyperglycemia, and prevention and treatment of bone loss remain major strategies, including lifestyle modifications, insulin or oral hypoglycemic agents, and anti-osteoporosis drugs." (PMID 40873948, 2025). "Hyperglycemia indirectly affects cancer cells by increasing circulating levels of insulin and insulin-like growth factor 1, which are associated with enhanced tumor cell proliferation and reduced apoptosis." (PMID 39812937, 2025). "AID is a potentially life-threatening metabolic disorder characterized by the progressive destruction of insulin-producing β-pancreatic cells by T lymphocytes, leading to impaired insulin production and hyperglycemia, two hallmark features of the disease." (PMID 40142026, 2025). "A 17-year-old girl presented with recurrent attacks of acute pancreatitis, associated with severe hyperglycemia and hypertriglyceridemia, despite being on intensive insulin therapy for the last 10 years." (PMID 39874659, 2025). "Loss of pancreatic beta-cells in type I DM causes insulin depletion, hyperglycemia, dysregulation of glucose homeostasis, and eventually death in uncontrolled diabetic patients and animals." (PMID 39883721, 2025).